RN7SL672P (RNA, 7SL, cytoplasmic 672, pseudogene)
Gene: Miscellaneous RNA gene on chromosome 20 (50,557,682 to 50,557,998, reverse strand). Ensembl gene ENSG00000239742.
Homologues: Orthologues: chimpanzee Metazoa_SRP (92% identical), macaque Metazoa_SRP (84% identical). Paralogues in human: RN7SL2 (81% identical), RN7SL1 (80% identical), RN7SL3 (79% identical), RN7SL127P (78% identical), RN7SL357P (77% identical), RN7SL788P (77% identical), RN7SL493P (77% identical), RN7SL296P (76% identical), RN7SL444P (76% identical), RN7SL478P (76% identical), RN7SL239P (76% identical), RN7SL45P (76% identical), and 702 more.